VTCN1 (V-set domain containing T cell activation inhibitor 1)
Diseases named in the same sentence as VTCN1 in open-access papers (continued):
Sharing a sentence is not in itself a finding about the gene and the disease.
tumor (298 papers, 2009 to 2026). "Further analysis revealed that immune checkpoint genes CD47, PVR, SIRPA, and VTCN1 were found to be elevated in the high-risk cohort, indicating their role in suppressing anti-tumor immunity." (PMID 40243557, 2025). "The biological activity of VTCN1 is associated with inflammatory CD4+ T-cell responses and VTCN1- expressing tumor-associated macrophages and FoxP3+ regulatory T cells (T regs) within the tumor microenvironment." (PMID 39116105, 2024). "VTCN1 is known as an immune checkpoint of B7 superfamily of co-stimulatory molecules, and the expression of VTCN1 on tumor associated macrophage was found to be related to the angiogenesis." (PMID 35906610, 2022). "Hypomethylation of the VTCN1 promoter leads to its high expression, which can cause tumor development by inhibiting CD8+ T cell infiltration." (PMID 35774278, 2022). "VTCN1 is intricately associated with various tumor metastases, which can be attributed to the inhibition of T cells in the tumor microenvironment." (PMID 34367975, 2021). "Studies have indicated VTCN1 expression was positively linked to tumor progression and acted as a candidate for the treatment of cancer." (PMID 33062039, 2020). "For example, SPP1 encoding osteopontin (OPN) and VTCN1 (aka B7-H4) are the genes known to be involved in cytokine production and negative regulation of T cell mediated immunity, suggesting a deficiency in T cell-mediated immunity in tumor associated CD4+ T cells." (PMID 34012510, 2021). "After further investigation of the expression profiles of ccRCC in TCGA data, VTCN1 was excluded from the analysis, as VTCN1 expression was lower in tumor tissues than in normal tissues." (PMID 40548645, 2025). "The expression levels of immune checkpoints, including BTLA, VTCN1, CD276, PDCD1, CD160, NRP2, and CD200, as well as the tumor-associated fibroblast marker FAP, were found to be higher in the high-risk group." (PMID 40364849, 2025). "VTCN1, also known as B7-H4, is abnormally upregulated in tumor cells and TAMs, and works as a negative regulatory factor of T cell immune response." (PMID 38225273, 2024). "Among immunoinhibitors, PVRL2, CD160, KDR and VTCN1 were also negatively correlated with LAMP3 expression in many tumours." (PMID 38146591, 2024). "VTCN1 was also identified as a tumor-enriched cell surface marker and is clinically relevant as antibody–drug conjugates targeting VTCN1 are currently being evaluated in clinical trials; however, this marker was not subtype specific." (PMID 39478117, 2024). "PVRL2 and VTCN1 have been studied in tumor-related immunotherapy by regulating the activity of immune cells." (PMID 39116105, 2024). "Overexpression of VTCN1 in tumors correlates with their clinicopathological features, and promotes tumor proliferation, metastasis and immune evasion." (PMID 38149244, 2023). "Serving as a negative regulator of T-cell-mediated antitumor immunity, VTCN1 can inhibit T cell activation and cytokine secretion, and regulate cytotoxic T lymphocytes (CTLs) during tumor progression." (PMID 37404825, 2023). "VTCN1 is an immunoregulatory protein that negatively regulates T cell-mediated immune response in the tumor microenvironment." (PMID 37404825, 2023). "CTLA4, HAVCR2, PVRL2, PDCD1, SIGLEC15, TIGIT, and VTCN1 expression levels were higher in tumor tissues, while CD244, LAG3, PDCD1LG2, and CD274 expression levels were found to be lower." (PMID 35923695, 2022). "VTCN1, also known as B7S1, is also a negative regulator of tumor immunity by various mechanisms such as dampening the anti-tumor Th1 responses." (PMID 35311155, 2022). "More importantly, the hypomethylation of promoter of VTCN1 led to its high expression, thereby induce tumor development by inhibiting CD8+ T cell infiltration." (PMID 35774278, 2022).
tumor (continued). "As a newly discovered immune checkpoint expressed on APC cells and tumor cells, VTCN1 is expected to become a novel target for immunotherapy in the future despite its regulatory mechanism in cancer immunity remained to be further explored." (PMID 33637086, 2021). "Upregulation of VTCN1 has been observed in various tumour tissues, and this is parallel with poor clinical and tumour aggressiveness pathological features." (PMID 33921181, 2021). "In PCa, an elevated level of VTCN1 is associated with activation of genes that establish cancer stem cells (CSC), pathological high tumour stage and poor or shorter OS rate, making it a potential independent prognostic biomarker and therapeutic target." (PMID 33921181, 2021). "Blockage of the interaction between VTCN1 and its receptors overcomes tumoral immune escape and correlates with increased T cells and NK cell infiltration that suppresses PCa tumour growth and metastasis." (PMID 33921181, 2021). "Because VTCN1 is differentially expressed in OvCa subtypes, we next evaluated the protein levels of B7S1 in tumor samples from primary debulking surgeries of 32 treatment-naïve patients with epithelial OvCa (Table." (PMID 34307455, 2021). "By averaging z‐score expression levels per tumor, tumors with DDR mutation had lower expression levels of CTLA‐4, IFNG, TNF, FAS, and VTCN1, and higher expression levels of IL6, IL1B, and IL12A compared with the DDR wild‐type ones." (PMID 31991061, 2020). "The high-response group exhibited elevated expressions of BTLA, LGALS9, PDCD1LG2, TIGIT, TNFSF15, and VTCN1 compared to the low-response group, suggesting that patients with this tumor profile may benefit from ICIs therapy." (PMID 40761787, 2025). "In addition, the expression of receptors, including TNFSF14, CD40, LTBR, and VTCN1, was elevated in LN-out tumor cells." (PMID 38519500, 2024). "VTCN1 can inhibit T cell activation and proliferation, negatively regulate T cell immune response, and its overexpression promotes tumor tolerance and might contribute to Treg development in a CRC tolerogenic milieu." (PMID 37404825, 2023). "VTCN1 is known to mediate immune homeostasis at several sites of inflammation, including those in the tumor microenvironment, and we hypothesized that it might also play an analogous role in maternal-fetal immune regulation." (PMID 37008954, 2023). "Furthermore, the VTCN1 expression was higher in the tumor group than in the normal group, and hypomethylation and high expression of VTCN1 indicated poor prognosis." (PMID 35774278, 2022). "In our study, we found that VTCN1 is downregulated in tumor tissue via DNA methylation analysis." (PMID 35774278, 2022). "The VTCN1 expression was higher in the tumor group than in the normal group." (PMID 35774278, 2022). "B7-H4 (B7S1, B7x, or Vtcn1), like B7-H3, is ubiquitously expressed by solid organs like the brain, kidney, liver, and spleen as well as immune cells particularly tumor-infiltrating antigen-presenting cells (APCs)." (PMID 33741032, 2021). "Other immune checkpoint ligands expressed by TAMs, with a potential direct suppressive effect on tumor-infiltrating T-cells, are B7-H4 (also known as B7x, B7S1 or VTCN1) and V-domain Ig-containing suppressor of T-cell activation (VISTA, also known as PD-1H, B7-H5, DD1α)." (PMID 33212945, 2020). "B7-H4 is a cell surface antigen encoded by the VTCN1 gene, meaning V-set domain containing T cell activation inhibitor 1 which interacts with ligands bound to receptors on the surface of T cells and has been correlated with tumor progression." (PMID 30781683, 2019). "However, VTCN1 negatively regulates T cell-mediated immunity and potentiates immune evasion, epithelial cell transformation, proliferation, cytokine production and the development of cytotoxicity by suppressing T cell activation in the tumour microenvironment." (PMID 33921181, 2021).
tumor (continued). "V-set domain-containing T-cell activation inhibitor 1 (aliases VTCN1, B7H4) participates in tumour immune escape by delivering inhibitory signals to T cells." (PMID 38732263, 2024). "Immune-cold tumor microenvironments are known to be characterized by low levels of PD-L1 and CTLA4 coupled with enhanced VTCN1 expression." (PMID 37388735, 2023). "In THCA tumor, CTLA4 (rho = 0.691), HAVCR2 (rho = 0.610), TIGIT (rho = 0.641), VTCN1 (rho = 0.618) showed remarkably positive with FAP expression." (PMID 37166418, 2023). "Of the 49 costimulatory molecules, 21 molecules (VTCN1) were upregulated and 28 molecules (TNFSF8) were downregulated in tumor tissues." (PMID 36646765, 2023). "We demonstrated that P4HA1 expression was positively correlated with the expression of TNFSF15, CD80, VTCN1, TNFSF18, and CD200R1 in multiple tumor types but negatively correlated with the expression of CD40LG and CD244." (PMID 35812752, 2022). "B7 superfamily member 1 (B7S1, also known as, B7-H4, B7x, or VTCN1) expressed by TAM has a direct role in the dysfunction of tumor-infiltrating T-cells, proinflammatory cytokine production, and cytotoxicity." (PMID 36679900, 2022). "Based on the clinicopathological negative association of B7-H4 expression and CD8+ TILs, the characteristics of VTCN1 in the tumor immune-response of HNSCC were further analyzed." (PMID 40586978, 2025). "Additional immune-checkpoints that may also contribute to tumor immune escape have been introduced such as CD47, B7-H3 (CD276), B7-H4 (VTCN1,B7X), CD39 and CD73." (PMID 38439112, 2024). "Secondly, given the frequent comparisons of the implanting fetus to an invasive tumor, we further hypothesized that VTCN1/B7-H4 could play a role in trophoblast invasion." (PMID 37008954, 2023). "The B7 immune checkpoint superfamily includes B7-1 (CD80), B7-2 (CD86), B7-H1 (PD-L1, CD274), PD-L2 (PDCD1LG2), B7-H3 (CD276), B7-H4 (B7-x, VTCN1), and the inducible costimulator ligand (L-ICOS, CD275), which act as ligands on the surface of tumor cells or antigen-presenting cells." (PMID 36983005, 2023). "As an important co-stimulatory molecule of the B7 family, B7-H4 (VTCN1) inhibits the response of T cells by interacting with unknown receptors on the surface of T cells, thereby mediating tumor immune escape." (PMID 34307135, 2021). "Aside from tumor cell-target therapeutics like anti-CD47 antibodies and PD-1 blockade, other macrophage-related checkpoints are also identified, such as CD40 agonists, B7-H4 (aka B7x, B7S1 or VTCN1) and V-domain Ig- containing suppressor of T cell activation (VISTA, aka PD-1H, DD1α)." (PMID 37426676, 2023). "In addition, metformin reduced the expression of several proteins related to immune responses, including VTCN1, a B7 family member involved in immune regulation, as well as IRF4, a regulator of lymphocyte growth and differentiation, leading to decreased tumor cell proliferation and metastasis." (PMID 33690729, 2021). "In addition, VTCN1 expression was not significantly correlated with tumor grade or tumor stage." (PMID 34307455, 2021). "However, VTCN1 expression was not significantly correlated with tumor grade and disease-free survival, an observation not consistent with protein levels, suggesting that it may be related to the mechanism of post-transcriptional regulation." (PMID 34307455, 2021). "The strong positive correlation of SNRPA1, TMED10, and PROM2 with suppressive immune regulators like IDO1 and VTCN1, and negative correlation with Th1 and MAIT cell infiltration, suggest that these genes may contribute to an immune-evasive tumor microenvironment." (PMID 40826138, 2025).
cancer (166 papers, 2008 to 2026). A tumor composed of atypical neoplastic, often pleomorphic cells that invade other tissues. "In esophageal squamous cell carcinoma, VTCN1 expression was associated with the expression of cancer stemness proteins (SOX9, LSD1, OCT4, LGR5) and an activated PI3K/AKT/NFκB pathway." (PMID 40175626, 2025). "A positive correlation was found between CDH18 and VTCN1, an immune checkpoint molecule associated with poor prognosis and cancer progression." (PMID 40017628, 2025). "B7-Homolog 4 (B7–H4, also called B7S1, VTCN1, and B7x) is another checkpoint that its overexpression is indicative of poor prognosis and is linked with cancer progression." (PMID 38144305, 2023). "In most studies, the neo expression of VTCN1/B7-H4 on cancer cells is associated with cancer progression and poorer prognosis." (PMID 37008954, 2023). "VTCN1, also named B7-H4, belongs to the co-stimulatory B7 family molecules and is associated with a poor prognosis in multiple cancer types." (PMID 36324565, 2022). "In line with the identification of VTCN1 as a promising target for cancer treatment, its expression was associated with a shorter FP (HR:1.45, 95% CI 1.04–2.03, log rank p = 0.026) and a poor OS (HR:1.28, 95% CI 1–1.62, log rank p = 0.045)." (PMID 35178045, 2021). "VTCN1 suppresses T-cell immunity and is associated with immune evasion in cancer." (PMID 39666439, 2025). "However, immune-competent subtypes in several cancer types had relatively lower expressions than immune-deficient subtypes, particularly VTCN1 in GBM and LAG3 and IDO1 in PCPG were significantly elevated in immune-deficient subtypes." (PMID 32533054, 2020). "Among the immunoinhibitory genes, VTCN1 expression level was positively correlated with SUSD4 expression level in many types of cancer." (PMID 38579174, 2024). "For cancer associated LR interactions from the immune-to-epithelial, the HGSOC patients had higher ITGA4_MDK and BTLA (to VTCN1 and TNFRSF14)." (PMID 38328306, 2023). "The ICs—PD-L1, Indoleamine 2, 3-Dioxygenase (IDO) and V-set domain-containing T-cell activation inhibitor 1 (B7H4)—are known to potentially be expressed in cancer cells with the capability to inhibit immune responses by interaction with immune cells." (PMID 36768480, 2023). "We also noticed that V-Set domain containing T-Cell activation inhibitor 1 (VTCN1) was negatively correlated with necroptosis levels in most cancers." (PMID 36170029, 2022). "Correlation analysis of FDX1 with checkpoint gene expression found a high correlation (p < 0.05) with tumor necrosis factor (TNF)–related immune genes (TNFRSF14, 15, 25) and CTLA4, PDCD1, CD274, NRP1, and VTCN1 in some kinds of cancers." (PMID 36061184, 2022). "Functional enrichment and GSEA analyses illustrated that VTCN1 was significantly involved in T-cell regulation, cancer-related pathways, and hallmarks in OvCa." (PMID 34307455, 2021). "B7x (VTCN1) was remarkably overexpressed in many human cancers, and it repressed the antitumor immune effect and regulated the escape from immunosurveillance." (PMID 33092083, 2020). "Other recently identified B7 family members whose overexpression correlate with poor cancer prognosis include B7H4 (B7x, B7S1, VTCN1) and B7H5 (PD-1H, VISTA, GI24, DIES1)." (PMID 31544130, 2017). "Furthermore, RBFOX2 expression showed a significant association with immunosuppressive genes like PD-L1, CTLA4, VTCN1, KDR, and TGFBR1 across different types of cancers." (PMID 38881877, 2024). "In the current study, we found there was a close correlation between LDHA and LDHB expression levels and multiple TIIC subsets, i.e., B cells, cancer-associated fibroblast, CD4+ T cells, CD8+ T cells, endothelial cells, and neutrophils, and massive immunoinhibitors such as VTCN1." (PMID 37547725, 2023). "Downregulation of VTCN1 expression in our in vitro model of peri-implantation human TB development shifted cells away from syncytialization and toward invasion, consistent with findings in some cancers." (PMID 37008954, 2023).
cancer (continued). "Analysis of RNA-seq data sets revealed positive correlations between Vtcn1, the gene name of B7x, and Foxp3 in multiple human cancers, as well as a highly statistically significant correlation in a pan-cancer analysis of 30 cancer types curated by The Cancer Genome Atlas (TCGA)." (PMID 35523809, 2022). "Moreover, elevated CXCL11 expression was related to increased immunosuppressive factors except for VTCN1 in almost all types of cancer except THYM." (PMID 35935945, 2022). "Functional annotations indicated that VTCN1 was involved in regulating T cell-mediated immune responses and participated in the activation of a variety of classic signaling pathways related to the progression of human cancer." (PMID 34307455, 2021). "These outliers (CD276, VTCN1) were present in all three cancer subtypes." (PMID 27683114, 2016). "Furthermore, a hypoxic environment was able to increase VTCN1 expression in human cancer cells." (PMID 40175626, 2025). "The ARMG risk score showed significantly positive relation with immunoinhibitors TGFB1 and VTCN1, and was negatively related with immunostimulators CD27, CD28, CD40LG, CD80, ENTPD1 and ICOS in pan-cancer." (PMID 38090588, 2023). "Our findings showed that MLKL was positively correlated with the expression of immune checkpoints such as PD1, PD-L1, PD-L2, and CTLA4 in most cancer types, except for ICOSLG, CD200, CEACAM1, HHLA2, and VTCN1 in BUC." (PMID 37000317, 2023). "The genes included in the high-expression group were VTCN1, CD200, CD276, and LGALS9, as they showed a higher expression level in all the cancer samples." (PMID 36157232, 2022). "Basal-A lines were characterized by expression of PROM1 (aka CD133), a marker of various cancer stem cells, as well as other genes like GABRP and VTCN1." (PMID 19582160, 2009). "Inflammatory cytokines that drive the expression of other B7-family members do not lead to the upregulation of VTCN1 on cancer cells, while immunosuppressive cytokines such as TGF-β1 and IL-10 do." (PMID 40175626, 2025). "The opposite effects were observed upon VTCN1 upregulation, suggesting that B7H4 may take part in the E7/Rb pathway during HPV infection, contributing to cancer development." (PMID 39061159, 2024). "B7x (B7-H4/B7S1/VTCN1), for example, is an inhibitory immune checkpoint molecule and is considered a potential therapeutic target because of its immunosuppressive effects and well-known expression in cancers." (PMID 32039002, 2019). "Importantly, expression of Cd80 was not significantly affected by either cancer cell medium or infection, and B7-H4 (Vtcn1) was very low in any of the experimental groups." (PMID 40547518, 2025).
infection (10 papers, 2009 to 2025). The state of being infected such as from the introduction of a foreign agent such as serum, vaccine, antigenic substance or organism. "VTCN1, a gene in endometrial spheroids, was downregulated by both decidualization and infection." (PMID 39666439, 2025). "VTCN1 was significantly downregulated by both infection and decidualization." (PMID 39666439, 2025).
VTCN1 also shares sentences with these, for which no sentence is quoted: gastric cancer (26 papers); colorectal cancer (19); lymph node metastasis (16); ovarian tumor (14); esophageal squamous cell carcinoma (10); non-small cell lung carcinoma (10); prostate carcinoma (10); rheumatoid arthritis (6); triple-negative breast carcinoma (6); colorectal tumor (5); type 1 diabetes (5); B-cell lymphoma (4); liver cancer (4); lymphoma (4); metastatic disease (4); renal carcinoma (4); small cell lung carcinoma (4); adenocarcinoma (3); Autoimmunity (3); cholangiocarcinoma (3); diabetes (3); esophageal cancer (3); intraepithelial neoplasia (3); Listeria monocytogenes infection (3); lung adenocarcinoma (3); metastasis (3); preeclampsia (3); acute myeloid leukemia (2); Arthritis (2); atherosclerosis (2).
A further 88 diseases each share a sentence with VTCN1 in 2 papers or fewer.